SSTR3 (somatostatin receptor 3)
Description:
Receptor for somatostatin-14 and -28. This receptor is coupled via pertussis toxin sensitive G proteins to inhibition of adenylyl cyclase.
Synonyms: SS-3-R; SS3-R; SS3R; SST3; SSR-28
Tractability: Small molecule: a high-quality ligand is known; it belongs to a druggable protein family. Antibody: its Gene Ontology location is reachable by antibodies, with high confidence; UniProt places it where antibodies can reach, with medium confidence; UniProt predicts a signal peptide or a membrane-spanning region. PROTAC: a small molecule that binds it is known. Other modalities: an approved drug acts on it.
Target class: Peptide receptor (family A GPCR); Membrane receptor; Short peptide receptor (family A GPCR); Family A G protein-coupled receptor; Somatostatin receptor
Chemical probes: BN-81644 (high quality), MK-4256 (high quality)
Gene: Protein-coding gene on chromosome 22 (37,204,237 to 37,212,477, reverse strand). Ensembl gene ENSG00000278195.
Subcellular location: Cell membrane
Subcellular location (Human Protein Atlas): Actin filaments; Plasma membrane; Primary cilium
Pathways (Reactome):
Signal Transduction: G alpha (i) signalling events; Peptide ligand-binding receptors
Organelle biogenesis and maintenance: BBSome-mediated cargo-targeting to cilium
Gene Ontology:
Molecular function: protein binding; G protein-coupled receptor activity; neuropeptide binding; somatostatin receptor activity; signaling receptor binding
Biological process: cell-cell signaling; G protein-coupled receptor signaling pathway, coupled to cyclic nucleotide second messenger; hormone-mediated apoptotic signaling pathway; negative regulation of cell population proliferation; neuropeptide signaling pathway; G protein-coupled receptor signaling pathway; somatostatin signaling pathway
Cellular component: cilium; ciliary membrane; neuron projection; non-motile cilium; plasma membrane; 9+0 non-motile cilium; membrane
Genetic constraint (gnomAD): Loss-of-function variants: 1 observed, 1.12 expected, observed/expected ratio (o/e) 0.89, 90% interval 0.25 to 1.88. That is too few expected variants to judge how well the gene tolerates losing a copy. Missense variants: 504 observed, 604.07 expected, observed/expected ratio (o/e) 0.83, 90% interval 0.77 to 0.9. Synonymous variants: 281 observed, 273.21 expected, observed/expected ratio (o/e) 1.03, 90% interval 0.93 to 1.13.
Homologues: Orthologues: chimpanzee SSTR3 (99% identical), macaque SSTR3 (98% identical), dog SSTR3 (89% identical), pig SSTR3 (88% identical), guinea pig SSTR3 (87% identical), rat Sstr3 (86% identical), mouse Sstr3 (85% identical), rabbit SSTR3 (71% identical), tropical clawed frog sstr3 (53% identical), zebrafish sstr5 (42% identical), Caenorhabditis elegans trhr-1 (19% identical), Drosophila melanogaster Rh7 (19% identical). Paralogues in human: SSTR5 (46% identical), SSTR2 (42% identical), SSTR1 (40% identical), SSTR4 (39% identical), OPRL1 (32% identical), NPBWR1 (30% identical), NPBWR2 (30% identical), OPRD1 (30% identical), OPRK1 (29% identical), OPRM1 (29% identical), KISS1R (27% identical), UTS2R (22% identical), and 5 more.
Diseases named in the same sentence as SSTR3 in open-access papers:
SSTR3 is named in the same sentence as 59 diseases in open-access papers, as found by Europe PMC text mining. Sharing a sentence is not in itself a finding about the gene and the disease. The quoted sentences say what the papers report.
pituitary adenomas (7 papers, 2017 to 2025). "SSAs such as Octreotide and Lanreotide, which bind to somatostatin receptor 2 (SSTR2), and to a lesser extent, to SSTR5 and SSTR3, are effective in the treatment of secreting pituitary adenomas, but are poorly efficacious in NFPAs." (PMID 37444563, 2023). "Moreover, besides pituitary adenomas, recent studies suggest an elevated SSTR3 expression in diverse neuroendocrine-related malignancies such as pancreatic tumors, pheochromocytomas, paragangliomas, lung carcinoids and breast cancer." (PMID 37444563, 2023). "Somatostatin receptor 3 expression was evaluated in 232 pituitary adenoma samples." (PMID 30627156, 2018). "Additionally, SSTR2A and SSTR3 were lower in recurrent PIT-1-positive pituitary adenomas (p = 0.0049 and p = 0.0212, respectively)." (PMID 30627156, 2018). "Previous reports of SSTR mRNA expression in GH-secreting pituitary adenomas in humans describe SSTR5 > SSTR2 whereas SSTR1 and SSTR3 expression can be highly variable and SSTR4 expression is absent." (PMID 30620005, 2019). "Of the 5 SSTRs identified, SSTR2 and SSTR3 are expressed in most nonfunctioning pituitary adenoma samples, whereas SSTR5 is only expressed in a minority of tumors." (PMID 40255441, 2025). "Like the other pituitary tumors, the expression of somatostatin receptor ligands in nonfunctioning pituitary adenoma is heterogenous, with SSTR3 being the abundant subtype in these tumors." (PMID 40255441, 2025). "Nonfunctioning pituitary adenomas (NFPAs), which express high levels of SSTR3 and show only modest response to currently available SSTR agonists, are often invasive and cannot be completely resected, and therefore easily recur." (PMID 37444563, 2023). "In a head-to-head comparison of octreotide and pasireotide in a rat model of spontaneous nonfunctioning pituitary adenoma, pasireotide showed a superior antitumor effect compared to octreotide, particularly in female rats, which also expressed more SSTR3 than males." (PMID 40255441, 2025). "In clinical studies of patients with nonfunctioning pituitary adenoma, octreotide had little effect on tumor mass reduction but was associated with stabilization of postsurgical tumor remnants; in these patients, the SSTR5 subtype was the most abundant in the tumor, followed by SSTR3." (PMID 40255441, 2025). "Paraffin-embedded tumor samples of 88 corticotroph pituitary adenomas and 30 nonadenomatous pituitary biopsies were analyzed after processing into tissue microarrays and immunohistochemical staining for SSTR 1, SSTR2A, SSTR3, SSTR4, and SSTR5." (PMID 30627156, 2018). "SSTR2A, SSTR3, and SSTR5 are highly expressed in corticotroph pituitary adenomas and differ from nonadenomatous tissue, providing a promising target for medical treatment with somatostatin analogs." (PMID 30627156, 2018). "SSTR3 expression was higher in corticotroph adenomas compared to PIT-1-positive, gonadotroph, and nonfunctioning pituitary adenomas (p < 0.0001, p = 0.0280, and p < 0.0001, respectively)." (PMID 30627156, 2018). "Given the potent antiproliferative, proapoptotic, and antiangiogenic activities of SSTR3, targeting this receptor with a multireceptor SSA such as pasireotide may be potentially beneficial in treating aggressive nonfunctioning pituitary adenoma." (PMID 40255441, 2025).
adenoma (6 papers, 2013 to 2023). A neoplasm arising from the epithelium. "Compared to a normal adrenal gland, ACC revealed an increase in almost all SSTR, while only some aldosterone-producing adenomas over-expressed SSTR3 and SSTR1." (PMID 37185426, 2023). "Adenomas developing in this model have a gender-specific SSTR3 expression pattern, with high expression levels of the receptor in females." (PMID 37444563, 2023). "A previous study from our group also found a lower SSTR2 mRNA expression in NFPA in comparison to somatotropinomas, however, the SSTR3 was similar in these adenoma subtypes." (PMID 24098585, 2013). "The expression of SSTR3 has also been reported from a few adenomas." (PMID 38203605, 2023). "Although previous studies have suggested that SSTRs other than SSTR2 are involved in this type of adenomas, studies involving other SST analogues like SOM230 should be further evaluated, as high expression levels of SSTR3 in these adenomas are of great relevance." (PMID 38203605, 2023). "Some other studies, however, have reported greater SSTR2 expression than SSTR3 or SSTR5 in SGAs and hormone-negative adenomas." (PMID 30020466, 2019). "Likewise, other studies have suggested that SSTR3 is the predominant SSTR expressed in hormone-negative adenomas and SGAs, both by IHC studies and mRNA levels, and SSTR2 expression was shown to be absent in another cohort of true null cell adenomas." (PMID 30020466, 2019).
glioma (4 papers, 2015 to 2023). A benign or malignant brain and spinal cord tumor that arises from glial cells (astrocytes, oligodendrocytes, ependymal cells). "The four selected AGs (LEP, TERT, PON1, and SSTR3) were concluded to have important functions in immune cell infiltration of glioma." (PMID 34114970, 2021). "A prognostic risk model was constructed according to four selected AGs (LEP, TERT, PON1, and SSTR3) in the TCGA dataset and Chinese Glioma Genome Atlas (CGGA) database." (PMID 34114970, 2021). "Consensus clustering analysis was used to sort glioma samples into two clusters according to the expression profile of four survival-associated AGs (TERT, LEP, PON1, and SSTR3)." (PMID 34114970, 2021). "The molecular mechanisms of PON1 and SSTR3 in glioma remained ambiguous." (PMID 34114970, 2021). "Our results revealed the expression of PON1 was crucially positive associated with SSTR3 in glioma, while there were a crucial negative association between the expression of PON1 and TERT, and the expression of LEP was negatively associated with PON1 and SSTR3." (PMID 34114970, 2021).
meningioma (4 papers, 2021 to 2024). A generally slow growing tumor attached to the dura mater. "Skull base meningiomas also reached the highest score for SSTR3 (2.2), while spinal and convexity/falx tumors had similar low mean scores (1.7 each, p < 0.0001)." (PMID 33899156, 2022). "However, the distribution of SSTR2 and SSTR3 was lower in feline meningiomas than in human meningiomas." (PMID 39011594, 2024). "SSTR3 was present in both normal meningeal tissue and in all cases of meningiomas." (PMID 34830858, 2021). "In canine meningiomas (n = 7), RNA expression of SSTR1, SSTR2 and SSTR5 was detected in all samples; SSTR3 RNA expression was detected in only 33% of samples." (PMID 39011594, 2024). "On the contrary, the analysis of SSTR3 and 4 expression showed higher mean scores in NF2 meningiomas." (PMID 33899156, 2022). "Therefore, we analyzed the distribution of 5 somatostatin receptors (SSTR1, SSTR2A, SSTR3, SSTR4, SSTR5) in a large meningioma cohort including patients suffering from NF2 and higher grade meningiomas." (PMID 33899156, 2022). "In feline meningiomas (n = 12), RNA expression of SSTR1, SSTR4, SSTR5 and SSTR2 was detected in 91%, 46%, 46% and 36% of samples, respectively; SSTR3 was not expressed." (PMID 39011594, 2024).
glioblastoma (3 papers, 2015 to 2023). The most malignant astrocytic tumor (WHO grade IV). "While autoradiographic binding studies have shown no SSTR expression in glioblastomas, immunohistochemistry (IHC) and western blot have detected increased expression of subtypes SSTR1, SSTR2, and SSTR3." (PMID 25977882, 2015).
pituitary tumor (3 papers, 2023 to 2025). A benign or malignant neoplasm affecting the pituitary gland. "Interestingly, SSTR3 levels in MENX rat pituitary tumors were found to be gender-specific, with higher expression observed in females." (PMID 37444563, 2023). "A recent experimental study has demonstrated that SSTR3 monoligands activate signaling mechanisms that reduce NF-PitNET cell viability and inhibit pituitary tumor growth in animal models expressing SSTR3, suggesting that it could be an efficacious treatment for NF-PitNETs." (PMID 37033229, 2023).
somatotropinomas (3 papers, 2013 to 2024). "The SSTR3 expression was higher in the NFPA than in the somatotropinomas and in the normal pituitaries (p=0.03 and 0.02, respectively)." (PMID 24098585, 2013). "The SSTR3 was higher in the NFPA than in the somatotropinomas and the normal pituitaries (p values of 0.03 and 0.02, respectively)." (PMID 24098585, 2013). "Somatostatin receptor subtype 5 mRNA was highest in somatotropinomas, followed by SSTR2 > SSTR3 >> SSTR1 >>> SSTR4." (PMID 39202532, 2024). "In somatotropinomas, the expression levels of SSTR5 were positively correlated with SSTR2 (r = 0.49, Spearman FDR adjusted P < 0.0001) and SSTR3 (r = 0.28, P = 0.03)." (PMID 29266696, 2018). "In somatotropinomas, SSTR5 was the predominant SSTR subtype detected, followed by SSTR2, SSTR3 and SSTR1." (PMID 29266696, 2018). "In respect to the SSTR, lower SSTR2 and higher SSTR3 mRNA expression levels were found in the NFPA compared with both the normal pituitaries and the somatotropinomas." (PMID 24098585, 2013). "ZAC1 and SSTR2 are underexpressed and SSTR3 is overexpressed in NFPA compared to those in somatotropinomas and in normal pituitaries, which might explain the lack of tumor shrinkage that is observed in response to commercially available SA therapy in patients with NFPA." (PMID 24098585, 2013).
Alzheimer disease (2 papers, 2021 to 2025). A progressive, neurodegenerative disease characterized by loss of function and death of nerve cells in several areas of the brain leading to loss of cognitive function such as memory and language. "In Alzheimer’s disease (AD) the ciliary receptors p75NTR, SSTR3, and 5HTR6 have been implicated in the progression of cognitive decline." (PMID 39747370, 2025). "Serotonin receptor 6 (HTR6) and somatostatin receptor 3 (SSTR3) are two brain-enriched ciliary GPCRs involved in cognition and pathologies such as Alzheimer’s disease and cancer." (PMID 33372037, 2021).
ciliopathies (2 papers, 2020 to 2023). "For example, the melanin-concentrating hormone receptor 1 (MCHR1) and somatostatin type 3 receptor (SSTR3) localize to the axoneme of neuronal cilia and are mis-localized in ciliopathy mouse models." (PMID 33214552, 2020). "A growing interest toward SSTR3 is also emerging in the field of ciliopathies." (PMID 37444563, 2023).
Cognitive impairment (2 papers, 2022 to 2025). Abnormal cognition is characterized by deficits in thinking, reasoning, or remembering. "However, SSTR3−/− mice displayed pronounced cognitive impairment in the Morris water maze test, as evidenced by their protracted search for the submerged platform." (PMID 39804991, 2025). "In order to explore potential targets of how ciliary SSTR3 may involve in cilium morphology, cognitive impairment, and AIS alterations, we performed RNA sequencing (RNA‐seq) of hippocampal tissues from 6‐month‐old adult control and SSTR3−/− mice." (PMID 39804991, 2025). "Our results corroborate these findings, showing that knockout of SSTR3 leads to cognitive impairment in spatial cue‐related tasks, albeit not in working memory." (PMID 39804991, 2025). "Indeed, removal of the ciliary-localized somatostatin receptor 3 (SSTR3) results in novel-object-recognition cognitive impairment without grossly affecting brain development." (PMID 36055200, 2022).
corticotroph adenomas (2 papers, 2018 to 2023). "However, SSTR3 expression is highly heterogeneous among the different histological variants of NF-PitNET with very low levels in silent corticotroph adenomas." (PMID 37033229, 2023). "SSTR3 targeting could be a good therapeutic candidate in NF-PitNET except for silent corticotroph adenomas, which express very low levels of this receptor." (PMID 37033229, 2023). "RT-PCR and IHC of five corticotroph adenomas congruently showed no detection of SSTR3 and SSTR4 while mRNA and IHC levels for SSTR5 were high." (PMID 30627156, 2018). "While SSTR2 and SSTR4 were not detectable in corticotroph adenomas, one out of three cases showed expression of SSTR1 and one out of two for SSTR3 and SSTR5." (PMID 30627156, 2018).
Hodgkins lymphoma (2 papers, 2020 to 2022). A heterogeneous group of malignant lymphoid neoplasms of B-cell origin characterized histologically by the presence of Hodgkin and Reed-Sternberg (HRS) cells in the vast majority of cases. "SSTR-3 and SSTR-5 were detected only in malignant specimens, such as rhabdomyosarcoma, Hodgkin lymphoma, acute lymphoblastic leukemia, and a single nonmalignant condition, hereditary spherocytosis." (PMID 33297556, 2020).
Hyperglycemia (2 papers, 2021 to 2023). An increased concentration of glucose in the blood. "It has high affinity for SSTR-1, SSTR-2, SSTR-3 and most importantly SSTR-5 and presents hyperglycemia as a common adverse effect, but experience in malignant INSs is very limited." (PMID 34199977, 2021). "What remains to be ascertained clinically is whether the higher agonistic activity on SSTR3 may allow us to define a dose at which full receptor engagement is observed in the absence of significant hyperglycemia." (PMID 37444563, 2023).
neuroendocrine tumors (2 papers, 2011 to 2015). "Somatostatin analogues, such as octreotide, which display high binding affinity to SSTR2 and lower affinity to SSTR5 and SSTR3 (affinity rank order: SSTR2 > SSTR5 > SSTR3) are efficacious in the treatment of neuroendocrine tumors and exhibit only mild toxicity." (PMID 21985599, 2011).
pancreatic cancer (2 papers, 2010 to 2015). "The expression rates of SSTR-2 mRNA in cancer and adjacent tissue of 108 patients with pancreatic cancer were 81.5% (88/108) and 97.2% (105/108), respectively; SSTR-3 mRNA expression rates were 69.4% (75/108) and 55.6% (60/108)." (PMID 25890201, 2015). "In addition, SSTR-3 mRNA expression was higher in pancreatic tumor tissue than the adjacent tissue of cancer, and the rate of positive expression decreases with increasing degree of differentiation trend." (PMID 25890201, 2015). "Our study is aimed at exploring the cause from different therapeutic effects of somatostatin and its analogs on human pancreatic cancer and their relationship between changes of SSTR-2 gene expression and expression of SSTR-2, SSTR-3, and SSTR-5 genes." (PMID 25890201, 2015). "In this study, we detected the expression of somatostatin receptor subtypes SSTR-2, SSTR-3, and SSTR-5 messenger RNA (mRNA) from 108 cases of cancer tissue and adjacent tissue in patients with pancreatic cancer using RT-PCR method." (PMID 25890201, 2015). "The expression of somatostatin receptor subtypes SSTR-2, SSTR-3, and SSTR-5 messenger RNA (mRNA) in 108 cases of cancer tissue and adjacent tissue in patients with pancreatic cancer was detected by reverse transcriptase polymerase chain reaction (RT-PCR)." (PMID 25890201, 2015). "Therefore, in relation to drug receptor binding affinity and organ-specific aspects, we studied SSTR-2, SSTR-3, and SSTR-5 expression in the pancreatic cancer." (PMID 25890201, 2015).
thymoma (2 papers, 2022 to 2024). A neoplasm arising from the epithelial cells of the thymus. "The importance of SSTRs in thymic tumors is still a matter of debate, as there is a difference between in vitro cultured cells and in vivo thymomas; SSTR3 seems to be the only one expressed in both cases, while SSTR1 and SSTR2 were detected only in vivo." (PMID 39329930, 2024). "In general, for thymomas, SSTR3 is the predominant receptor, and it is presumed that the absence of endogenous somatostatin, and hence its permanent inactive state, leads to uncontrolled proliferation." (PMID 39329930, 2024). "Completely different from the pattern of healthy cells, thymomas were found to mostly express SSTR3." (PMID 39329930, 2024).
acromegaly (1 paper, 2023). Acromegaly is an acquired disorder related to excessive production of growth hormone (GH) and characterized by progressive somatic disfigurement (mainly involving the face and extremities) and systemic manifestations. "If we assume that the effects of the drugs are correlated with the expression of their target receptors, we would expect beneficial results from targeting SSTR3 in NF-PitNETs at least at similar levels as observed when targeting SSTR2 in acromegaly." (PMID 37033229, 2023).